NT5E (5'-nucleotidase ecto)
Diseases named in the same sentence as NT5E in open-access papers (continued):
Sharing a sentence is not in itself a finding about the gene and the disease.
tumor (1,045 papers, 1991 to 2026). "In our study, we analysed total EV content in the serum, including both tumour and immune cell derived EVs and found that a high CD73/NT5E expression on EVs was linked to PR." (PMID 41581122, 2026). "This is largely due to increased expression and activity of two key ectoenzymes, CD39 (ENTPD1) and CD73 (NT5E), on the surface of tumor cells, cancer-associated fibroblasts, endothelial cells, regulatory T cells (Tregs), and certain myeloid subsets." (PMID 41514547, 2025). "CD73 expression in tumor cells, the protein encoded by NT5E, was described to be associated with poorer outcomes." (PMID 40461625, 2025). "CD73 is encoded by the gene NT5E and plays a role in numerous tumor cell intrinsic and extrinsic functions." (PMID 37033953, 2023). "The NT5E gene encodes CD73, known as an ectonucleotidase, which plays a crucial role within tumor cells, with immune-suppressive properties." (PMID 38067409, 2023). "Compared to normal samples, the mRNA expression of NT5E (encoding CD73 protein) is significantly elevated in tumor samples (P = 9.7×10-10)." (PMID 36466881, 2022). "In terms of mechanism, circ_ASAP2 directly targeted miR-330-3p to upregulate the expression of ecto-5′-nucleotidase (NT5E), which is associated with tumor invasion and metastasis." (PMID 35127685, 2022). "Some of the tumor-associated proteins with differential levels in comparison to all the control types include 5′-nucleotidase isoform 2 (NT5E), aminopeptidase N (ANPEP)." (PMID 34876625, 2021). "Consistently, NT5E/CD73 expression is higher in liver metastasis than in primary tumour or normal mucosa and is significantly linked with TAMs expression profile but not with the MMR status." (PMID 24741617, 2014). "Numerous studies in a variety of murine tumour models have also highlighted that loss of NT5E/CD73 function can efficiently delay tumour growth and confer metastasis resistance." (PMID 24741617, 2014). "However, the model requires further refinement, particularly in elucidating the underlying biological mechanisms of ATP6V1C2, SRPX, and NT5E to better comprehend their roles in tumor progression and patient prognosis." (PMID 40463372, 2025). "Clinical verification of three tumor-associated proteins with elevated levels in comparison to all the three control types—5′-nucleotidase isoform 2 (NT5E), aminopeptidase N (ANPEP) and neprilysin (MME) was carried out using individual plasma samples from early or advanced stage GBC." (PMID 34876625, 2021). "Since high levels of NT5E/CD73 expression on tumor cells are significantly associated with reduced disease free survival (DFS) and overall survival (OS), and negatively correlate with tumor infiltration by immune cells, NT5E/CD73 targeting could be a promising strategy to reprogram the TME." (PMID 33613285, 2020). "Subsequent single-cell analysis identified NT5E as a key regulator of the tumor microenvironment that promotes cancer progression." (PMID 41487509, 2025). "It has been reported that NT5E (CD73) generates extracellular adenosine, mediates immune escape, and promotes tumor growth and metastasis, making it a crucial target for immunotherapy." (PMID 40078192, 2025). "Moreover, ENHO’s negative correlations with other immune checkpoint molecules, such as CD276 (B7-H3) and NT5E (CD73), which are implicated in immune escape by suppressing T-cell activity and promoting regulatory T-cell (Treg) responses, further reinforce its potential anti-tumor role." (PMID 40647442, 2025). "Among the downstream targets of HIF1α, NT5E (CD73), an ecto-5′-nucleotidase, plays a pivotal role in the tumor microenvironment by converting extracellular AMP to immunosuppressive adenosine." (PMID 41463265, 2025). "Results indicated that NT5E (CD73) mRNA expression was notably higher in HNSCC tumor tissues compared to normal tissues." (PMID 40078192, 2025). "Ecto-5′-nucleotidase (NT5E, also known as CD73) is implicated in modulating anti-tumour immune responses." (PMID 40612859, 2025).
tumor (continued). "The production of extracellular adenosine in the tumor microenvironment is linked to poor patient outcomes and is driven by high expression of the ectonucleotidases CD39 (ENTPD1) and CD73 (NT5E)." (PMID 40519286, 2025). "Future studies using 3D organoid or in vivo xenograft models of EAC will be essential to determine the physiological relevance of dual (HIF1α and NT5E) inhibition on tumor growth, angiogenesis, immune modulation and metastasis." (PMID 41463265, 2025). "Through differential gene analysis, we found that the NT5E and KIF20A genes, which are highly related to tumor development, were differentially elevated in the high-risk group." (PMID 39091494, 2024). "For example, upregulated expression of ecto-5′-nucleotidase (NT5E), also designated as CD73, increases extracellular levels of immunosuppressive adenosine, which inhibits tumor attack by activated T cells." (PMID 37409119, 2023). "CD73 is encoded by the gene NT5E and is crucial in numerous tumor cell-intrinsic and extrinsic functions." (PMID 38067409, 2023). "In contrast, expression of genes correlated with worse survival and hypoxia (PANX1, NT5E, ADORA2B, and P2RY2) was associated with tumor cells and the squamous PDAC subtype, correlating with hypoxia, inflammation, and worse prognosis." (PMID 36942939, 2023). "exATP is converted to ADO by CD39 and NT5E/CD73, and while exATP promotes anti-tumor immunity, ADO attenuates it." (PMID 36741002, 2023). "Consistent with the observed defect in mitochondrial respiration, CD73 NT5E gene-targeted tumor cells also displayed reduced ratios of ATP to ADP or AMP." (PMID 37261423, 2023). "From another aspect, researches have probed in murine tumor models that anti-CD73 antibody therapy and blockade of A2A receptors potently inhibit outgrowth of NT5E expressing tumors." (PMID 36091055, 2022). "We note that three targetable immune checkpoint proteins (B7-H3, NT5E and PD-L2) are expressed at higher levels in C2 tumours." (PMID 36207323, 2022). "Gene NT5E encodes the ecto-5’-nucleotidase (CD73), which facilitates the formation of immunosuppressive tumor microenvironment (TME) permissive for tumor progression in various malignancies." (PMID 36091055, 2022). "Ecto-5′-nucleotidase (CD73, also known as NT5E) is a cell surface ectoenzyme, which is expressed in multiple cell types, including tumor cells, stromal cells, and immune cells." (PMID 35132961, 2022). "In sarcoma tumours harboring a high NK cell gene signature, NT5E (encoding for CD73) gene expression was negatively associated with survival." (PMID 35565201, 2022). "NT5E, an ecto-nucleotidase, is a component of purinergic signaling and plays an important role in tumor cell escape from immune system." (PMID 34876625, 2021). "We observed increased expression of 5 immune suppressive genes including PVR (CD155), TGFB1, NT5E (CD73), VEGFA, and CD276 (B7-H3) in 9p21-loss tumors across multiple tumor types/subtypes when compared to 9p21-WT tumors." (PMID 34556668, 2021). "NT5E is involved in cellular interaction with ECM proteins such as laminin and fibronectin and NT5E overexpression is known to support tumor proliferation, migration, angiogenesis, and immune escape." (PMID 33690729, 2021). "Hypoxia is also a hallmark feature of the TME known to regulate NT5E expression and is shown to induce CD73 expression and adenosine production promoting tumor progression." (PMID 33430239, 2021). "The same group showed that the PTC/adjacent paired expression ratio of NT5E mRNA was associated with metastatic lymph nodes and tumor size and that all PTC (n = 29) were CD73-positive by immunohistochemistry (IHC)." (PMID 34019179, 2021). "To further dissect the association between transcriptional up-regulation of CD73 (NT5E) and unfavorable clinical outcomes in PTC, we performed tumor microenvironment profiling based on RNA-seq data." (PMID 33086655, 2020).
tumor (continued). "Third, our results suggest that pathways other than the NT5E gene methylation are involved in the regulation of CD73 expression in the tumor microenvironment, but studies on the specific mechanisms involved are lacking." (PMID 33198064, 2020). "An increase in NT5E/CD73 expression is also found in Tregs from the spleen of P2×7−/− tumor-bearing mice." (PMID 33613285, 2020). "HIF1A in turn regulates transcription of NT5E/CD73 whose involvement in tumor development is widely documented as well as those in adaption to hypoxia and promotion of immune-escape." (PMID 32443824, 2020). "Deregulation of selected genes (Arg1, C7, Lcn2, Nt5e, and Tgfb1) from preinvasive lesion to overt cancers (classical tumours and PDC) was orthogonally confirmed by qPCR." (PMID 31439856, 2019). "GBM is an uncurable tumor associated with a profoundly immunosuppressive pathology and characterized by upregulation of the ectoenzyme CD73, the product of the NT5E gene." (PMID 31547570, 2019). "Among most upregulated genes in classical tumours, Nt5e, Tgfb1, and Arg1 have been consistently associated to T cell disfunction." (PMID 31439856, 2019). "To comprehensively parse the roles of hypoxia in MDSC accumulation in tumors, we investigated the ENTPD family and NT5E, which have been currently demonstrated as the important contributors in the immunosuppressive tumor microenvironment." (PMID 28894087, 2017). "CD73 is a glycosylphosphatidylinositol (GPI) anchored cell surface protein that is encoded by NT5E gene, plays multiple roles in tumor processes." (PMID 28915673, 2017). "In cancers, NTPD1 and NT5E, through creating an adenosine-rich tumor microenvironment, enable immune cells to escape immune surveillance and promote tumor survival." (PMID 28894087, 2017). "Extracellular 5′-AMP is known to be catabolized into adenosine by ectoenzyme NT5E (CD73), which is widely expressed in endothelial cells, epithelial cells, several immune cells (mainly Treg cells and MDSCs), as well as tumor cells." (PMID 28894087, 2017). "In particular, 12 genes, including AXL, CDH1, CFLAR, FKBP1A, NT5E, and VIM, were reported to be significantly associated with tumor metastasis (P<8E-04)." (PMID 23185353, 2012). "In terms of function, NT5E may be involved in purine-metabolism reprogramming, influencing the metabolic states of tumor cells and their surrounding cells, and thus regulating cell-cell communication and interaction." (PMID 40236698, 2025). "Particularly, NT5E (CD73)—a key ectoenzyme that generates extracellular adenosine- promotes an immunosuppressive tumor microenvironment by inhibiting antitumor immune responses and facilitating metabolic crosstalk between cancer cells and cancer-associated fibroblasts." (PMID 41007761, 2025). "The upregulation of NT5E expression is predominantly mediated by hypoxia-inducible factors within the tumor microenvironment, coupled with a complex network of pro-inflammatory cytokines and soluble mediators that collectively establish a permissive niche for its transcriptional activation." (PMID 40612859, 2025). "This indicates that NT5E plays a vital role in the inter-cellular signal communication between tumor cells and CAF, promotes the malignant progression of PC, and thus emerges as a key intermediate mediator in the purine-metabolic reprogramming and the formation of an immunosuppressive environment." (PMID 40236698, 2025). "CD73 encoded by NT5E gene can catalyze AMP to adenosine, and adenosine produced by hydrolysis can induce immunosuppression and angiogenesis, which is a novel target for tumor immunotherapy." (PMID 39002018, 2024). "In addition, genes that were upregulated in tumor-derived iCAFs were associated with the regulation of the inflammatory response, namely, IL6ST, NFKBIA, NT5E, SERPINF1, and NFKBIZ, suggesting that they play roles in communicating with immune cells." (PMID 34976204, 2022).
tumor (continued). "Similarly, overactivation of the PI3K-Akt pathway is also an important mechanism of tumour growth and invasion, which shows the role of NT5E in tumour progression and suggests that NT5E is a potential target." (PMID 35510041, 2022). "Quercetin has been also reported to modulate the activity of some members of the multidrug-resistance transporters family, such as P-gp, ABCC1, ABCC2, and ABCG2, and the activity of ecto-5′-nucleotidase (NT5E/CD73), a key regulator in some tumor processes such as invasion, migration, and metastasis." (PMID 33918012, 2021). "NT5E is a ubiquitously expressed glycosylphatidylinositol-fixed glycoprotein, which can convert extracellular adenosine 5′-monophosphate to adenosine, and promote tumor development by inhibiting the anti-tumor immune response and promoting angiogenesis." (PMID 33462260, 2021). "Overexpression of NT5E can promote tumor proliferation, migration and invasion." (PMID 34906153, 2021). "In PTC, a recent study reported that CD73 (NT5E) mRNA overexpression was associated with lymph node metastasis and tumor size in a small series of cases (n = 29), and led the authors to suggest that studies with a larger number of patients are required to clarify their preliminary findings." (PMID 33086655, 2020). "Among ATP receptors, the P2X7R is the subtype most convincingly associated to tumor growth, and at the same time involved in the modulation of NTPDase1/CD39 and NT5E/CD73 expression in the TME." (PMID 33613285, 2020). "Independently, increased mRNA expression of ENTPD1 (CD39) and NT5E (CD73) in the CD8− inflamed tumor subtype could signal an adenosine-rich TME, further contributing to CD8+ T cell exclusion in these tumors." (PMID 31675502, 2019). "In light of its immune suppressive function and due to its expression by various tumor entities, such as melanoma, triple-negative breast cancer, colorectal cancer (CRC), and non-small cell lung cancer, NT5E has been considered as target checkpoint molecule for novel tumor immunotherapy approaches." (PMID 29720980, 2018). "Blocking NT5E/CD73 signaling could have two important effects: to rescue the endogenous adaptive antitumour immune responses and to inhibit the metastatic potential of tumour cells." (PMID 24741617, 2014). "These include NT5E (CD73) and ENTPD1 (CD39) which are involved in immunosuppressive adenosine signaling, LGALS1 (galectin-1) and TGFB1, which encode for anti-inflammatory cytokines, and CD274 (PD-L1), which binds to PD-1 to initiate an inhibitory signaling pathway in anti-tumor immune cells." (PMID 40277917, 2025). "Three proteins, NT5E, ANPEP and MME, were selected for clinical verification based on differential abundance in GBC compared to all control types (healthy, GSD and XGC cases), their association with tumor state in other cancers and functional relevance to tumor condition." (PMID 34876625, 2021). "Thus, hypoxia resulting from uncontrolled tumor cell proliferation might induce HIF1A mediated up-regulation of NT5E expression on GSCs." (PMID 32443824, 2020). "Systemic administration of a P2X7R antagonist to tumor-bearing WT mice reduces tumor growth and upsets the immune infiltrate causing on one hand an increase in CD4+ and Teff cells, and on the other a down-modulation of both NTPDase1/CD39 and NT5E/CD73 expressed by CD8+ Treg cells." (PMID 33613285, 2020). "NT5E (CD73), functioning as an ectonucleotidase, catalyzes the conversion of AMP to adenosine and represents a core molecule in tumor immunosuppression." (PMID 40236698, 2025). "The five-gene signature’s expression was validated utilizing the TCGA database, with NT5E, HSP90AA1, and EIF2AK3 demonstrating elevated expression levels in tumor tissues, while PIK3CA and P2RX7 exhibited heightened expression in normal tissues." (PMID 38575204, 2024).
tumor (continued). "Expression of NAMPT, NAPRT, NT5E and QPRT were quantified by qPCR and Western blot in both established and primary GBM cell lines, and IHC was performed on sections from GBM tumours for the same proteins." (PMID 38893173, 2024). "Among the five identified ICDGs, NT5E, HSP90AA1, and EIF2AK3 exhibited heightened expression levels in tumor tissues, while PIK3CA and P2RX7 demonstrated elevated expression levels in normal tissues." (PMID 38575204, 2024). "We also examined the distribution of each gene in the 5-gene signature in GGO cells and discovered PLD4, NT5E and MAOB were differentially expressed between cancer cells and non-tumor cells, suggesting a more critical physiological significance." (PMID 38434969, 2024). "The scoring signature is constructed by three genes (IL1A, NT5E, and TLR7), whose expression in the tumor is significantly higher than normal both in the TCGA cohort and our PKUCH cohort." (PMID 36979463, 2023). "The authors genetically deleted Nt5e/CD73 in murine PDAC cells and used an orthotopic model to show deletion of CD73 significantly ablated tumor growth and reduced the abundance of infiltrating MDSCs." (PMID 37187740, 2023). "Reduced expression of eight immune‐related genes (IRGs) (NT5E, THRA, RBP1, TLR4, ITGA6, BMPR1B, ITGAV, SSTR1) in tumor strongly predicted better quality of prognosis, both in our patient cohort and in TCGA‐HNSC cohort." (PMID 37392167, 2023). "First, PHLDA1 was positively correlated with the infiltration levels of a variety of immunocompetent tumor-infiltrating cells, including Act CD4, CD56dim, and Act DC, and 23 types of immune promoters, including IL6, NT5E, and TNFSF9." (PMID 36142223, 2022). "For example, PHLDA1 was positively correlated with the infiltration levels of a variety of immunocompetent tumor-infiltrating cells, including Act CD4, CD56dim, and Act DC and 23 types of immune promoters, including IL6, NT5E, and TNFSF9." (PMID 36142223, 2022). "In these immunostimulatory marker genes, CD276, MICB, NT5E, PVR and ULBP1 had a significantly positive correlation with RRM2 expression in most tumor types." (PMID 35740608, 2022). "This correlates with elevated expression of the rate-limiting adenosine producing enzyme NT5E, more commonly known as CD73, on multiple cells in the TME including tumor and immune cells." (PMID 34832904, 2021). "GGCT expression was significantly upregulated in tumor tissues, while AOX1, NT5E, PPP1R12A, and PTGS2 were significantly downregulated compared to normal tissues in the TCGA cohort." (PMID 34484299, 2021). "Cancer exosomes are reported to express NT5E (or CD73) and CD39, leading to extracellular adenosine in tumor microenvironment and suppress T Cells27." (PMID 34876625, 2021). "A combination of drugs targeting NT5E/CD73 and the A2A adenosine receptor has been shown to potentiate anti-tumor immune responses decreasing tumor growth and metastatic spreading." (PMID 33613285, 2020). "Tumor microenvironment plays vital roles in shaping cancer diversity, and CD73 (ecto-5′-nucleotidase; NT5E) is an emerging immune checkpoint in modulating cancer progression via conversion of immunostimulatory ATP into immunosuppressive adenosine." (PMID 32205841, 2020). "Because tumor hypoxia-induced cell death leads to elevated ADO in the TME29,30,35, we then cultured CAFs in the presence of ADO, which markedly elevated Nt5e expression within 24 h." (PMID 31980601, 2020). "As was consistent with the qRT-PCR results, SPP1, COL1A1 and NT5E proteins were up-regulated, while the expression of HTRA1 and ANGPT1 were down-regulated in the tumor compared with ANPT groups (n = 29)." (PMID 27690016, 2016). "In our analysis eight new candidate tumor suppressor genes were identified, OXSR1 (3p22.2), BSG(19p13.3), NT5E(6q14.3), PLEKHG7(12q22), CMTM8(3p22.3), NETO2(16q12.1), ODZ3(4q35.1) and ERBB4(2q34)." (PMID 25551557, 2014).